TG (thyroglobulin)
Diseases named in the same sentence as TG in open-access papers (continued):
Sharing a sentence is not in itself a finding about the gene and the disease.
hypothyroidism (continued). "In hypothyroidism, DQA1*001:01 is more frequently found in dogs with thyroglobulin autoantibodies (OR = 2.57; 95% confidence interval = 1.28–5.17)." (PMID 26618927, 2015). "Laboratory investigations revealed hypothyroidism (free triiodothyronine 1.55 pg/mL, free thyroxine 2.9 pg/mL, TSH 452 mU/L, thyroglobulin 20.1 ng/mL)." (PMID 22672871, 2012). "Anti-Thyroglobulin (ATG) was detected in 29% and Anti-thyroid peroxidase (ATPO) in 21% of the patients; of these children, 14% had hypothyroidism." (PMID 20444250, 2010). "In the study reported by Elgazar and colleagues, 200 patients with Type-II DM, 11.1% of women with overt hypothyroidism, 57.2% were positive for thyroid antibodies, which were 42.9% positive for anti-TPO alone, 0% for anti-TG alone, and 14.3% positive for both antibodies." (PMID 40735558, 2025). "Therefore, the total number of patients included for hypothyroidism was 6,035 (four articles), anti-TPO, 6,069 (four articles), anti-TG, 443 (three articles), altered TSH, 96 (one article), and mean TSH, 6,071 (four articles)." (PMID 37598033, 2024). "Patient A was also diagnosed with hyperthyroidism and secondary hypothyroidism with negative antibodies against thyroglobulin protein, thyroid peroxidase, and thyroxine receptor, indicating an autoinflammatory condition." (PMID 37273692, 2023). "Furthermore, in 2019, our team revealed that ER stress decreased thyroglobulin and contributed to HFD‐induced hypothyroidism." (PMID 33943005, 2021). "For discrimination between transient and permanent CH patients with gland in situ, there was no clinical or laboratory parameter including gestational age, birth weight, presentation time, age at onset of therapy, or the degree of hypothyroidism based on serum levels of TSH, fT4, and thyroglobulin." (PMID 27086592, 2016). "HT was diagnosed as follows: 1) medical history or clinical biochemistry evidence of hypothyroidism requiring thyroid hormone replacement therapy, and 2) presence of autoantibodies to thyroidperoxidase, with or without antibodies to thyroglobulin." (PMID 26329403, 2015). "The initial presence of goiter and elevated thyroglobulin antibodies, the presence of celiac disease, and a progressive increase in thyroperoxidase antibodies and TSH value predict a progression toward overt hypothyroidism." (PMID 25436160, 2014). "However, given her TSH normalized weeks later and she had neither thyroglobulin antibodies nor thyroid peroxidase antibodies, this was thought to represent euthyroid sick syndrome rather than hypothyroidism." (PMID 38744309, 2024). "Interestingly, thyroid peroxidase antibody and thyroglobulin antibody have been evaluated in all cases with ScH and overt hypothyroidism, and both were negative." (PMID 36295508, 2022). "Despite no significant changes in subclinical hyperthyroidism or hypothyroidism or anti-thyroid peroxidase or anti-thyroglobulin antibody positivity prevalence, a significant increase in thyroid nodule prevalence (P < 0.0001) was found in the overall population." (PMID 34762596, 2021). "For hypothyroidism, the first two features in the disease-specific ITCs were the TSHB (thyroid stimulating hormone beta) and TG (thyroglobulin), both of which were not included in the disease's genes." (PMID 39897058, 2025). "Among patients with anti-TPO and anti-TG antibodies, the group infected with HTLV-1 had a significantly greater proportion of biological hypothyroidism than the group that was not, but this observation was based on a small sample." (PMID 37293205, 2023). "A dose of 100 mCi of 131I was administrated in hypothyroidism (TSH 80 mU/ml, thyroglobulin 32 ng/ml, anti-thyroglobulin antibody negative) and whole body scan showed hyper fixation in mediastinal, median cervical region and diffuse fixation in lungs (pT3 N1b M1)." (PMID 16672060, 2006).
thyroid (372 papers, 1990 to 2026). "Correlations were significantly associated between SWE scores and anti-thyroglobulin (TgAb), thyroid volume, mean hemoglobin A1c (HbA1c), and time elapsed from a diagnosis of CD." (PMID 42074643, 2026). "This study combined thyroglobulin and thyroid function tests to see their impact on identifying more patients who are at risk for thyroid disorders in pregnancy." (PMID 40969723, 2025). "Lipopolysaccharide-induced Toll-like receptor activation is associated with the development of thyroiditis or the production of anti-thyroglobulin antibodies in mice." (PMID 38027117, 2023). "For instance, the risk of developing nivolumab-destructive thyroiditis is known to be significantly higher in patients with pre-treatment anti-thyroid antibodies (namely, anti-peroxidase and anti-thyroglobulin antibodies)." (PMID 35721217, 2022). "Excess of iodine can anticipate and exacerbate the occurrence of spontaneous thyroiditis in genetically predisposed animals, by increasing the immunogenicity of thyroglobulin (Tg)." (PMID 33914231, 2021). "They found no remarkable differences in clinical outcomes between observation and treatment groups of patients with DTC with thyroid bed on diagnostic WBS despite undetectable thyroglobulin levels." (PMID 30944403, 2019). "Serum 25(OH)D concentrations <125 nmol/L were associated with an increased risk of thyroid disease, a 115% increased risk of elevated anti-TG antibody, 118% increased risk of anti-TPO antibody and 107% increased risk of elevated TSH." (PMID 29067607, 2017). "Throughout follow-up examinations, an excellent association between the presence of normal and/or malignant thyroid tissue and serum stimulated thyroglobulin (Tg) levels has been noted." (PMID 24963446, 2014). "Serum free T4, free T3, thyrotropin (TSH), thyroglobulin, thyroglobulin antibody, antimicrosomal antibody, tumor-associated status, and thyroid disorders were documented." (PMID 23496874, 2013). "Others are associated with autoimmune kidney disease (GBM), thyroid disorders (thyroglobulin), scleroderma (PM/Scl100), and inflammatory arthritis (proteoglycan)." (PMID 21366908, 2011). "Our study found that the pathogenesis of thyroiditis induced by exogenous thyroglobulin injection in mice may be associated with T-cell imbalance and the activation of pro-inflammatory immune factors, which aligns with established research models." (PMID 40909293, 2025). "Furthermore, autoimmune thyroid diseases, particularly the presence of thyroid autoantibodies such as anti-thyroid peroxidase and anti-thyroglobulin, have been reported to be significantly associated with moyamoya-like vasculopathy." (PMID 41441210, 2025). "Excess iodine can cause increased thyroglobulin iodization and stimulate the production of oxygen free radicals, which promote the metastasis of inflammatory cells, activate thyroid cell apoptosis, and lead to thyroiditis." (PMID 34570342, 2022). "Thyroid-associated antibodies such as TPOAb, thyroglobulin antibody (TgAb), thyrotropin [thyroid-stimulating hormone (TSH)] receptor antibody (TRAb or TSHRAb), and α-enolase antibody targets for cortical neurons and endothelial cells were found in HE patients with epilepsy." (PMID 31133960, 2019). "This retrospective study aimed to estimate the prognostic validity of thyroid autoantibodies, thyroglobulin (Tg), and the thyroid disease type in diagnostic approaches regarding the co-existence of incidental thyroid carcinoma (ITC) with benign thyroid diseases." (PMID 24348554, 2013). "Mechanism of thyroid toxicity may be that lithium is concentrated in the thyroid gland and damages follicular cells, causing release of thyroglobulin into the circulation." (PMID 22991519, 2012). "One radiographic feature that is reported in literature is the fact that ectopic thyroid appears as hyperdense on CT and hyperintense on MR T1, this is thought to be due to the presence of thyroglobulin." (PMID 41357818, 2025).
thyroid (continued). "HT is diagnosed by the presence of positive specific Thyroid Antibody Titers (TAT), Anti-thyroid Peroxidase (TPO), anti-thyroglobulin (Tg), as well as thyroid ultrasound, a complementary method that can be used in the evaluation of thyroid disorders." (PMID 41228508, 2025). "Anti-thyroid antibodies, including anti-thyroperoxidase (TPO) and anti-thyroglobulin (TG) antibodies, have also been implicated in RSA." (PMID 39859499, 2025). "We analyzed serum thyroid biomarkers, including serum vitamin D, anti-thyroglobulin (TG) antibody, and anti-thyroid peroxidase (TPO) antibody for patients with HT." (PMID 41113708, 2025). "Assessment of anti-thyroid antibodies (anti-thyroperoxidase, anti-thyroglobulin, and anti-TSH receptor) is helpful in identifying autoimmune thyroid diseases." (PMID 39648292, 2024). "There was not a statistically significant change in the number of patients that presented at least one positive autoantibody for thyroiditis (anti-TG or anti-TPO, p = 0.06) or type 1 diabetes (anti-IAA, anti-IA2, anti-Zn-T8, or anti-GAD, p = 0.15)." (PMID 38892641, 2024). "SREAT is linked to autoimmune thyroiditis, including Hashimoto's thyroiditis, and is frequently associated with positive serum anti-thyroid antibodies, including anti-thyroid peroxidase (anti-TPO) and anti-thyroglobulin antibodies." (PMID 39473654, 2024). "Our results indicate that the expression of PCDH8 is significantly associated with the type of primary neoplasm focus, the PFI, history of thyroid gland disorders, methylation levels, age, race, pathologic stage, and thyroglobulin levels." (PMID 38368303, 2024). "The usefulness of thyroglobulin levels in initial evaluations of TNs is limited because patients with thyroid disorders (especially multinodular diseases) often have similar thyroglobulin levels to those with thyroid cancer." (PMID 38352091, 2024). "The histopathology of the resected mass showed the characteristics of ectopic thyroid, and immunohistochemical staining revealed positive expression of thyroid transcription factor-1 and thyroglobulin." (PMID 38711853, 2024). "The latest study found that Midkine/free thyroxine (MK/FT4) and Midkine/thyroglobulin (MK/TG) in FNA washing fluid have diagnostic value for papillary thyroid carcinoma, especially thyroid nodules with uncertain cytology." (PMID 37608676, 2024). "Risk factors for GO-related elevated IOP included older age, longer duration of thyroid disease, and higher anti-thyroglobulin values." (PMID 38535069, 2024). "CD4EM T cells have been shown to contribute to thyroiditis development in anti-PD-1 treated mice with preexisting autoimmunity following anti-thyroglobulin immunization." (PMID 37794264, 2023). "During the disease process, anti-thyroglobulin and anti-thyroperoxidase antibodies against exposed thyroid antigens were continuously produced." (PMID 36740672, 2023). "Biochemical markers of thyroid autoimmunity, i.e., anti-TG or anti-TPO Ab positivity or thyroiditis diagnosed by ultrasonography, were significantly higher and more frequent in patients with psoriatic arthropathy." (PMID 38192953, 2023). "Antibodies such as thyroid peroxidase antibody (TPOAb), anti-thyroglobulin (TGAb), anti-TSH receptor (TSAb), and anti-microsomal antibodies are positive in autoimmune causes of thyroid disorders." (PMID 36788909, 2023). "TCONS_00044048 antisense binding target gene ncbi_100750237 (symbol: TG, thyroglobulin) significantly enriched thyroid synthesis and autoimmune thyroid disease pathways, indicating that TCONS_00044048 plays an important role in thyroid disease." (PMID 36672927, 2023). "Before initiating RAI therapy, it poses a significant challenge to distinguish structural or functional disease from thyroid remnants or biochemical disease based on serum thyroglobulin (sTg) levels." (PMID 38298190, 2023).
thyroid (continued). "Although anti-TPO Ab and anti-TG Ab were elevated in psoriasis and control subjects, there was no statistical significance when the two groups were compared based on thyroid auto-antibodies." (PMID 38192953, 2023). "The other tests for thyroid antibodies and thyroglobulin identify autoimmune thyroid conditions and thyroiditis, respectively." (PMID 37343156, 2023). "High levels of anti-thyroid peroxidase (Anti-TPO) and anti-thyroglobulin (Anti-TG) antibodies indicate that this thyroid disease occurs due to a disorder in the immune system." (PMID 36810529, 2023). "Thyroid pathology in the form of postpartum thyroiditis is particularly prevalent in patients with positive anti-thyroperoxidase and anti-thyroglobulin antibodies." (PMID 35844617, 2022). "This study aimed to investigate the relationship of thyroid autoimmune bodies (thyroid peroxidase antibody [TPOAb] and thyroglobulin antibody [TgAb]) with CAD in euthyroid subjects undergoing coronary angiography." (PMID 36181027, 2022). "Of interest, treating NOD.H2h4 mice with blocking antibodies to PD-1 and to CTLA-4 markedly enhances thyroiditis and autoantibodies to thyroglobulin and TPO." (PMID 35572553, 2022). "Two independent Swedish studies demonstrated that patients with DMab-associated T1D had a higher risk of anti-CCP positive RA and of anti-thyroid peroxidase and anti-thyroglobulin positive thyroiditis." (PMID 36429105, 2022). "Eight patients with abnormal results of TSH or a history of thyroid disease were positive to at least one thyroid autoantibody (anti-TPO or anti-TG)." (PMID 35984815, 2022). "Eight (34.8%) patients were found to have abnormal thyroid functioning, including elevated thyroid peroxidase antibodies (17.4%), increased anti-thyroglobulin antibodies (13.0%), and increased total triiodothyronine and thyroxine (8.7%)." (PMID 34234736, 2021). "After resection of the thyroid lesion, the patient's serum thyroglobulin levels were markedly decreased." (PMID 31937367, 2020). "Thyroid-associated antibodies such as thyroperoxidase (TPO) antibody, thyroglobulin (TG) antibody, and thyrotropin receptor (TR) antibody were found in HE patients with seizure disorders." (PMID 31133960, 2019). "HE/SREAT is not necessarily associated with hypo- or hyperthyroidism but serum anti-thyroid antibodies seem to present ubiquitary in these patients whereas CSF thyroperoxidase (TPO) and thyroglobulin (TG) antibodies are rarely positive." (PMID 30524441, 2018). "In a second step, we defined a more selective reference group (SRG, n = 170) by excluding patients with thyroiditis pattern on thyroid ultrasound and positive anti-thyroglobulin antibodies." (PMID 30304102, 2018). "The level of iPTH in the aspirated cystic fluid was much higher than that in the serum, although thyroid cystic fluid is known to contain high levels of thyroglobulin." (PMID 30123260, 2018). "Autoimmune thyroid disorders are predominantly associated with the presence of thyroid autoantibodies directed to TPO and thyroglobulin." (PMID 28575127, 2017). "Diagnosis for Graves' disease, toxic nodular goiter, and postpartum thyroiditis was mostly clinical with only 20% of the patients able to afford thyroid autoantibody (thyroglobulin, thyroid peroxidase) testing." (PMID 28326101, 2017). "Serum thyroglobulin concentrations increase with age, smoking, alcohol intake, thyroid disorders, and the presence of thyroid nodules, in addition to iodine insufficiency." (PMID 27455319, 2016). "Anti-thyroid antibodies (anti-thyroid-peroxidase antibody and anti-thyroglobulin antibody) were heavily increased." (PMID 26209970, 2015). "Significant gender differences were found for eight investigated factors, six of which were predominant in women (Raynaud's phenomenon, thyroiditis, anti-SS-B, anti-DNA, anti-TG, and anti-TPO) and two in men (polyarthritis, RF)." (PMID 24963499, 2014).
thyroid (continued). "Carbohydrate composition as well as sialic acid concentration differs in thyroglobulin of normal and pathologic thyroid tissue." (PMID 25003133, 2014). "The measurement of thyroglobulin antibodies has proven to be clinically less rewarding in postpartum thyroiditis." (PMID 23691429, 2013). "In addition, there are many benign thyroid conditions (e.g., thyroiditis, thyrotoxicosis, benign adenoma and iodine deficiency) that may cause a false-positive reading, as reflected by increased thyroglobulin levels." (PMID 24281099, 2010). "The patient had co-existing acetylcholine receptor-antibody positive myasthenia gravis (treated with pyridostigmine) and thyroglobulin and thyroid peroxidase antibody positive thyroiditis." (PMID 20825655, 2010). "Because IgG4 is the main subclass deposited in MN, the subclass of anti-thyroglobulin and anti-thyroperoxidase antibodies should be determined in the patients with thyroiditis-related GN." (PMID 18853201, 2009). "Immunohistochemical thyroglobulin positivity is a useful tool in distinguishing between a thyroid primary and other metastatic lesions, as this marker is specific for thyroid tumours." (PMID 18782440, 2008). "One patient with thyroiditis developed anti-thyroglobulin antibodies, the serology of all other patients was normal." (PMID 2390468, 1990). "The detection of thyroglobulin in the biopsy determines a thyroid origin of the tissue." (PMID 39744583, 2025). "Serum levels of thyroid-stimulating hormone (TSH), free thyroxine (fT4), free triiodothyronine (fT3), and thyroid antibodies (anti-thyroid peroxidase antibodies (aTPO), anti-thyroglobulin antibodies (aTG)) were measured, and muscle strength was assessed using hand-held dynamometry." (PMID 40332280, 2025). "Preoperative thyroid-related laboratory tests were all within normal ranges, including free triiodothyronine, serum free thyroxine, thyroid-stimulating hormone, anti-thyroid peroxidase antibody, anti-thyroglobulin antibody, and thyroglobulin levels." (PMID 41568262, 2025). "Clinically, this endotype may justify targeted screening for thyroid autoimmunity (anti-TPO, anti-TG), while non-thyroid autoantibodies are insufficiently studied and require prospective validation." (PMID 40943118, 2025). "Notably, 2 out of 3 patients with anti-thyroglobulin auto-antibodies developed a clinically significant thyroiditis requiring levothyroxine therapy after 1.1 and 2.8 years of ropegIFNα2b therapy, respectively." (PMID 38771499, 2024). "Autoimmune thyroid diseases (AITDs) are significant autoimmune disorders affecting thyroid function, which are diagnosed by the presence of autoantibodies against thyroid antigens, such as thyroglobulin antibodies (TGAbs) and thyroid microsomal antibodies (TMABs)." (PMID 39456701, 2024). "In AITD, thyroid peroxidase (TPO) and thyroglobulin (Tg) antibodies may also cross the placenta, potentially interfering with maternal and fetal thyroid function." (PMID 39434884, 2024). "Thyroid peroxidase antibody (TPO-Ab) and thyroglobulin antibody (TG-Ab) are autoantibodies targeting thyroid antigens and are considered important clinical markers for Hashimoto’s thyroiditis (HT), with positivity rates of approximately 75% and 90% in HT patients, respectively." (PMID 39363900, 2024). "The major thyroid autoantigens are thyroglobulin, thyroid stimulating hormone receptor and TPO." (PMID 38013274, 2023). "Thyroid function test alteration may be present, along with peroxidase and anti-thyroglobulin anti-thyroid antibodies, and should be monitored during ICI therapy to guarantee the appropriate diagnosis and treatment of thyroid toxicity." (PMID 37232813, 2023). "In addition, the cell proliferation antigen also has a certain expression in the process of thyroid lesions, especially in thyroid papillary carcinoma, which is closely related to the specific tumor size and thyroglobulin antibody." (PMID 37152372, 2023).